RNU6-739P (RNA, U6 small nuclear 739, pseudogene)
Gene: Small nuclear RNA gene on chromosome 3 (64,511,755 to 64,511,857, forward strand). Ensembl gene ENSG00000212340.
Homologues: Orthologues: macaque U6 (97% identical), rat LOC120101205 (72% identical), dog U6 (71% identical). Paralogues in human: RNU6-1113P (87% identical), RNU6-1020P (85% identical), RNU6-11P (85% identical), RNU6-19P (85% identical), RNU6-24P (85% identical), RNU6-28P (85% identical), RNU6-37P (85% identical), RNU6-43P (85% identical), RNU6-560P (85% identical), RNU6-854P (85% identical), RNU6-86P (85% identical), RNU6-1083P (84% identical), and 1286 more.